SPG7 (SPG7 matrix AAA peptidase subunit, paraplegin)
Diseases named in the same sentence as SPG7 in open-access papers (continued):
Sharing a sentence is not in itself a finding about the gene and the disease.
Spastic paraplegia (30 papers, 2009 to 2025). Complete loss of the ability to move the lower limbs accompanied by spasticity of the lower limbs. "Mutations of SPG7 are predominantly autosomal recessive; however, heterozygous SPG7 mutations have also been reported in association with diverse clinical manifestations such as optic atrophy, spastic paraplegia, and peripheral neuropathy." (PMID 38549004, 2024). "Another independent study reported that parkinsonism is frequently observed in spastic paraplegia patients with pathogenic variants in SPG7." (PMID 32172343, 2020). "SPG7, ATP-dependent zinc metalloprotease is involved in development of spastic paraplegia while BRD2 gene microdeletion is associated with juvenile myoclonic epilepsy development." (PMID 28423529, 2017). "Mutations in the mitochondrial m-AAA protease genes cause two different neurodegenerative diseases in humans: loss of function of SPG7 is associated with an autosomal recessive form of spastic paraplegia, whereas missense mutations in AFG3L2 have recently been associated with SCA28." (PMID 20426821, 2010). "Mutations in SPG7 cause Hereditary Spastic Paraplegia 7 (OMIM #607259), which typically presents as pure spastic paraplegia but is often associated with complex phenotypes." (PMID 39420034, 2024). "In the past, complex recessive spastic paraplegias have been frequently associated with SPG11 mutations but also with defects in SPG15, SPG7 and a handful of other rare genes." (PMID 27544499, 2016). "SPG7 (also called paraplegin) is a gene associated with spastic paraplegia in humans and would initially not seem to be a plausible drug resistance gene." (PMID 38886371, 2024). "A similar situation has been observed for the SPG7 gene, with the initial identification of rather mild optic atrophy in recessive SPG7 patients with spastic paraplegia, followed later by the identification of dominant SPG7 variants in patients with restricted Dominant Optic Atrophy." (PMID 35885985, 2022). "The patient (Proband No. 31) with SPG7 frameshift variant had a visual impairment since the age of 6 years but had no symptoms of spastic paraplegia." (PMID 34573359, 2021). "Myoclonus is rarely described in SPG, affecting patients with SPG4, SPG7, SPG35, SPG48, and SPOAN (spastic paraplegia, optic atrophy, and neuropathy)." (PMID 38035585, 2023). "Multiple CNVs affecting SPG7 (n = 4), CACNA1A (n = 3), SGCE (n = 3), NKX2-1 (n = 2) and SPAST (n = 2) were detected in individuals with episodic ataxia, dystonia, or spastic paraplegia, respectively." (PMID 36781956, 2023). "We identified two cases of spastic paraplegia (SPG), specifically SPG15 (ZFYVE26) and SPG7 (SPG7), with SPG15 showing a bigger and broader phenotypic onslaught compared to SPG7 in the form of seizures, hearing loss, and cerebellar atrophy." (PMID 32999401, 2020). "Genetic tests performed before WES excluded Huntington’s disease (IT15), spinal muscular atrophy (SMN1), spinal bulbar muscular atrophy (AR), primary torsion dystonia (DYT1), and the common forms of spastic paraplegias (SPG4, REEP1, ATL1, SPG7)." (PMID 25957632, 2015). "Both AFG3L2 and SPG7 are involved in a neurodegenerative disease, namely the autosomal dominant spinocerebellar ataxia SCA28 and a recessive form of spastic paraplegia, respectively." (PMID 20426821, 2010). "Treatment of SPG7 patient cells and Spg7 knockout neurons with Bz-423, a functional mimic of CyPD able to restore normal PTP openings, normalized synaptic transmission and motor performance in Spg7 knockout mice, providing a potential therapy for this form of spastic paraplegia." (PMID 37408243, 2023).
hereditary spastic paraplegia (29 papers, 2009 to 2026). Hereditary spastic paraplegias (HSP) comprise a genetically and clinically heterogeneous group of neurodegenerative disorders characterized by progressive spasticity and hyperreflexia of the lower limbs. "SPG7 is associated with hereditary spastic paraplegia overlapping with mitochondrial disease features." (PMID 40194557, 2025). "Paraplegin, encoded by SPG7, is an ATP-binding metalloprotease involved in the ‘quality control’ of mitochondrial membrane-bound protein, and mutations in this gene cause AR hereditary spastic paraplegia." (PMID 35203288, 2022). "Mutations in human SPG7 cause the neurological disorder hereditary spastic paraplegia, a distal axonopathy characterized by the loss of corticospinal motor neurons, and deletion of the SPG7 gene in mice also results in axonal and synaptic alterations." (PMID 29467464, 2018). "SPG7 is the disease-causing gene of hereditary spastic paraplegia but could occasionally lead to isolated optic atrophy." (PMID 34573359, 2021). "Mutations in AFG3L2 are associated with dominant spinocerebellar ataxia (SCA28) characterized by the loss of Purkinje cells, whereas mutations in SPG7 cause a recessive form of hereditary spastic paraplegia (HSP7) with motor neurons of the cortico-spinal tract being predominantly affected." (PMID 29451229, 2018). "Furthermore, disruption in the mitochondrial proteome control surveillance system caused by a mutation in SPG7 that encodes a m-AAA subunit has been reported for an autosomal recessive form of hereditary spastic paraplegia." (PMID 27417535, 2016). "The m-AAA displays a hexameric ring structure that in humans can be a homo-oligomer formed by AFG3L2 only, or a hetero-oligomer formed by AFG3L2 and Paraplegin (a paralog of AFG3L2 encoded by the SPG7 gene, whose loss-of-function causes an autosomal recessive form of hereditary spastic paraplegia)." (PMID 23777634, 2013). "Finally, we show that the previously generated mouse model of Spg7-linked hereditary spastic paraplegia is an isoform-specific knock-out, in which mitochondrial paraplegin is specifically ablated, while expression of paraplegin-2 is retained." (PMID 22563492, 2012). "It is important to note that mutations in the genes affected (SPG4, SPG7) result in various forms of hereditary spastic paraplegia (HSP)." (PMID 27375925, 2016). "Mutations in the SPG7 gene are the most frequent causes of autosomal recessive Hereditary Spastic Paraplegias (HSP) and spastic ataxias." (PMID 26506339, 2015). "SPG7-related hereditary spastic paraplegia (SPG7-HSP) is one of the most common forms of autosomal recessive HSP." (PMID 41656397, 2026). "SPG7 was initially identified as causing autosomal recessive hereditary spastic paraplegia (HSP), with a pure (insidiously progressive bilateral leg weakness and spasticity) and complex (with additional neurologic features including cerebellar signs and optic atrophy) forms." (PMID 41149856, 2025). "In patient-derived fibroblasts we quantified 124 morphological features in 100,000 cells from 15 people with two genotypes (SPAST and SPG7) of Hereditary Spastic Paraplegia (HSP) and matched controls." (PMID 34404843, 2021). "Bladder dysfunction was seen in three patients, which has been reported in ∼50% of patients with SPG7-related hereditary spastic paraplegia." (PMID 24727571, 2014). "For example, mutations in AFG3L2 lead to spinocerebellar ataxia type 28, or spastic ataxia 5; mutations in paraplegin are the causative agents of hereditary spastic paraplegia and progressive external ophthalmoplegia; and mutations in both AFG3L2 and SPG7 occur in dominant optic atrophy (DOA)." (PMID 34360841, 2021). "Mutations in SPG7 and SPAST are common causes of hereditary spastic paraplegia (HSP)." (PMID 32973427, 2020).
optic atrophy (22 papers, 2011 to 2025). A disorder characterized by loss of optic nerve fibers. "Clinically, the presentation of SPG7-associated DOA resembles other etiologies of optic atrophy, such as DOA from OPA1 or optic atrophy from Wolfram syndrome." (PMID 41149856, 2025). "The pathophysiology behind optic atrophy seen in SPG7-associated disorders stems from mitochondrial dysfunction." (PMID 41149856, 2025). "Optic atrophy occurred in 3/49 cases of SPG7 in a Dutch cohort; two SPG7 mutated sibs with optic atrophy manifested severe vision loss as the presenting symptom evolving to full blindness in the course of the illnesses." (PMID 38390227, 2023). "Yet, optic atrophy is found associated with spastic paraplegia linked to recessive mutations in SPG7, the paralog of AFG3L2 encoding another component of the m-AAA protease involved in OPA1 proteolytic maturation." (PMID 26539208, 2015). "Conversely, why is it that only some patients with MFN2 and SPG7 mutations develop visual failure and optic atrophy?" (PMID 21112411, 2011). "Knowledge of the different manifestations of SPG7-associated disease is crucial for both neurologists and ophthalmologists, and SPG7 should be considered in the work-up of patients presenting with entities such as optic atrophy, PEO, and cerebellar eye signs." (PMID 41149856, 2025). "It is therefore likely that optic atrophy is common in SPG7-mutated patients but the clinical significance of this remains unclear." (PMID 30533525, 2018). "In addition, genetic analysis of a large family with isolated optic atrophy disclosed the first dominant SPG7 mutation, c.1232A>C, p.D411A, affecting the AAA domain, 56 amino-acids upstream of the conserved RPGR motif, in which we found the AFG3L2 mutation." (PMID 26539208, 2015). "Concerning SPG7, most recessive patients with primary spastic paraplegia also present optic atrophy, whereas in the single family reported with a dominant SPG7 mutation, patients had isolated optic atrophy." (PMID 26539208, 2015). "After excluding variants in mitochondrial DNA and other nuclear genes associated with optic atrophy (e.g., OPA1, AFG3L2), the compound heterozygous SPG7 variants p.Val180Met and p.Gly349Ser were identified." (PMID 41149856, 2025). "Optic atrophy can be associated with HSP, but later studies also identified SPG7 as the cause of isolated dominant optic atrophy (DOA) and other ocular motor abnormalities, including various forms of nystagmus and ocular duction range limitations." (PMID 41149856, 2025). "The primary clinical prototype that was considered as a differential diagnosis for the phenotype presented by the patient in our case report, which includes spastic ataxia, ophthalmoparesis, and optic atrophy, is represented by SPG7 (MIM #607259)." (PMID 40757543, 2024). "SPG7 often displays a complicated phenotype, including optic atrophy, ophthalmoparesis, and impaired emotional communication." (PMID 35637455, 2022). "The variants in SOX5 (n = 1), SPG7 (n = 1), and SSBP1 (n = 1) genes were responsible for cases of other dominantly inherited optic atrophies." (PMID 36071901, 2022). "Seven patients out of 33 sporadic HSPs (21.2%) received a genetic diagnosis: five harbored mutations in SPAST, one case had biallelic variants in SPG7, and a young woman manifesting with HSP + early onset optic atrophy harbored a nonsense variant in OPA1." (PMID 33669240, 2021). "In contrast, the recessive variants identified in SPG7 (8.47%), OPA1 (5.08%), and SLC25A46 (1.69%) were associated with syndromic optic atrophies." (PMID 33841295, 2021). "Other phenotypes of SPG7 variants induce CPEO, optic atrophy, and muscle showing multiple mtDNA deletions." (PMID 33426505, 2020). "Optic atrophy, recognized as part of a more severe SPG7 complex phenotype, was seen in two patients in our cohort resulting in significant visual impairment." (PMID 24727571, 2014).
optic atrophy (continued). "Variants in SPG7 can lead to both autosomal recessive pure HSP, with insidiously progressive bilateral leg weakness and spasticity, and complex HSP, which often presents with additional features of optic atrophy and cerebellar eye signs." (PMID 41149856, 2025). "SPG7 has, therefore, to be considered in patients with late-onset cerebellar signs or optic atrophy, even in the absence of spasticity." (PMID 25758904, 2015). "One patient with SPG7 was diagnosed with optic atrophy but was not excluded from the analysis as optic atrophy was regarded as part of the multidegenerative process in complex HSP that is subject of this study." (PMID 23176075, 2012).
spastic ataxia (18 papers, 2011 to 2026). "A different study of 42 patients with biallelic SPG7 pathogenic variants reported that MRI T2 hyperintensities in the dentate nucleus of the cerebellum, as well as a characteristic phenotype of spastic ataxia were a predictor of SPG7-associated HSP." (PMID 41149856, 2025). "In the Chinese population, sporadic cases of SPG7 variant-associated spastic ataxia are rarely reported." (PMID 35637455, 2022). "We hereby report the molecular characterization and the clinical features of a large Cypriot family with five affected individuals presenting with spastic ataxia in an autosomal recessive transmission mode, due to a novel SPG7 homozygous missense variant." (PMID 35096021, 2021). "Recent reports detected MRI features mimicking the “eye of a tiger” sign, most commonly associated with pantothenate kinase e-associated neurodegeneration (PKAN), in SPG7 and the closely related spastic ataxia 5 (AFG3L2-mutated) patients." (PMID 34901147, 2021). "Multiple mutations in SPG7 have been described to cause HSPs and spastic ataxias, and an important role of this protein in neuronal mitochondrial function is assumed also clincially." (PMID 26506339, 2015). "Mutations in the SPG7 gene are the most frequent cause of autosomal recessive hereditary spastic paraplegias and spastic ataxias." (PMID 26506339, 2015). "Spastic ataxias refer to disorders in which most patients have a clinical presentation with equal contribution of pyramidal and cerebellar involvement such as in spastic ataxia of Charlevoix-Saguenay, and in SPG7, SAX2, SPG43 and RNF170 mutation carriers ((Synofzik and Schüle, 2017)." (PMID 34901147, 2021). "In addition, the SPG7 variants we identified and those previously reported, often had a similar phenotype of spastic ataxia but we also highlight the prominent opthalmoplegia (Choquetet al., 2015)." (PMID 27217339, 2016). "These patients exhibited diverse phenotypes, often with late onset, including ALS‐like features and SPG7‐related symptoms such as spastic ataxia." (PMID 39978794, 2025). "If validated longitudinally, the measures are prime candidate outcomes for future treatment trials for SPG7 and other spastic ataxias." (PMID 39621946, 2024). "The patient’s observed phenotypes are consistent with SPG7-related pathologies, which encompass both complicated and pure forms, with some carriers even receiving a diagnosis of spastic ataxia." (PMID 38239855, 2023). "Here we report the clinical, genetic, and neuropathological findings in a homozygous Ala510Val SPG7 case with spastic ataxia." (PMID 26506339, 2015). "Screening of the entire SPG7 and AFG3L2 genes in genetically undiagnosed cases of MND and spastic ataxia may help to increase the diagnostic yield." (PMID 41877227, 2026).
Parkinsonism (10 papers, 2009 to 2025). Characteristic neurologic anomaly resulting from degeneration of dopamine-generating cells in the substantia nigra, a region of the midbrain, characterized clinically by shaking, rigidity, slowness of movement and difficulty with walking and gait. "SPG7 pathogenic variants impair mitochondrial homeostasis owing to mitochondrial DNA abnormalities, which represents a possible link explaining the parkinsonism symptoms frequently observed in patients affected by this disease." (PMID 40194557, 2025). "In 2018, levodopa-responsive parkinsonism has been described in two HSP caused by SPG7 alterations (SPG7-HSP) patients." (PMID 40362688, 2025). "Cases presenting with levodopa-responsive parkinsonism in association with biallelic SPG7 mutations have been previously reported." (PMID 39420034, 2024). "Additional reports described the same clinical features of parkinsonism in patients with SPG7 mutations." (PMID 37648940, 2023). "In a study evaluating parkinsonism in 33 patients with pathogenic SPG7 mutations, De La Casa-Fages and colleagues found 7 patients with parkinsonian signs, with bradykinesia being the most frequently observed." (PMID 37648940, 2023). "Furthermore, the clinical spectrum of SPG7 continues to broaden, and recent years have seen a connection between SPG7 mutations and parkinsonism." (PMID 37648940, 2023). "Mutations in SPG7 gene result in multiple mtDNA deletions, and manifest phenotypically as mitochondrial disorders characterized by spasticity, ataxia, dysarthria, dysphagia, cognitive impairment, neuropathy, ophthalmoplegia, muscle wasting, sphincter dysfunction, and parkinsonism." (PMID 40362688, 2025). "Despite Spastic paraplegia type 4 being the most frequent form of HSP, recent studies have shown the emergence of parkinsonism as one of the symptoms to investigate, especially in SPG7 and SPG11, two HSPs with autosomal recessive transmission." (PMID 37648940, 2023). "Intriguingly, for some specific mutations in genes related to other phenotypes (e.g. hereditary dementias, SCAs, POLG-related ataxias, SPG7) parkinsonism may even represent the core clinical manifestation at the onset, making molecular diagnosis difficult." (PMID 37648940, 2023). "This unique link between mitochondrial proteostasis, cristae architecture, and axonal development differentiates SPG7 from PD genes that primarily regulate mitophagy or respiratory function, and places it within a broader neurodegenerative spectrum associated with atypical parkinsonism." (PMID 40362688, 2025).
Spastic paraplegia 7 (7 papers, 2015 to 2025). "Furthermore, two affected males, CZS_18 and CZS_25, carried a pathogenic variant (rs61755320; MAF gnomAD: 0.0029) that promotes an Alanine to Valine modification in the SPG7 gene causing spastic paraplegia 7 (OMIM #607259)." (PMID 34125832, 2021). "Spastic paraplegia 7 (SPG7, OMIM#602783), as one of the most common form of autosomal recessive hereditary spastic paraplegia (ARHSP) caused by mutations in the SPG7 gene, was firstly identified in 1998." (PMID 30497413, 2018). "The variant identified in SPG7 p.(Ala510Val) (MIM 602783) has previously been described in individuals with spastic paraplegia 7 (MIM 607259), and another SPG7 variant, c.1232A>C, p.(Asp411Ala), segregated with the disease in a family with an autosomal dominant optic neuropathy." (PMID 32040484, 2020).
Cerebellar atrophy (6 papers, 2018 to 2022). Cerebellar atrophy is defined as a cerebellum with initially normal structures, in a posterior fossa with normal size, which displays enlarged fissures (interfolial spaces) in comparison to the foliae secondary to loss of tissue. "Although cerebellar atrophy is known to be a hallmark of SPG7, a specific pattern of gray matter cerebellar atrophy that affects long-distance regions of the brain was recently shown to be associated with cognitive and social-ability impairment." (PMID 33817696, 2021). "Brain MRI findings in SPG7 mutation carriers included cerebellar atrophy and patterns suggestive of frontotemporal dementia." (PMID 32447552, 2020). "Cranial MRI revealed vermis atrophy in SPG7 variant carriers MD087 and VALS008, and two others (TALS012-01, VALS020) showed a cerebellar atrophy pattern, clinically manifesting as intention tremor in patients VALS008 and VALS020." (PMID 32447552, 2020). "Cerebellar dysfunction was also clinically observed in SPG7 variant carriers VALS125 (saccadic pursuit) with no correlating cerebellar atrophy on brain MRI at the time of investigation, TALS002-01 (ataxic gait) and MD018 (saccadic pursuit, nystagmus) with no available brain MRI." (PMID 32447552, 2020).